BAG3 (BAG cochaperone 3)
Diseases named in the same sentence as BAG3 in open-access papers (continued):
Sharing a sentence is not in itself a finding about the gene and the disease.
cancer (continued). "For example, the screened genes, such as EMP2 and BAG3, have become prevalent targets for cancer therapeutic studies, which have been discussed in the Results, but they were not included in the current cancer gene list." (PMID 34693378, 2021). "In addition, nucleotide-exchange factor BAG3 also showed to play a role in regulation of survivin and p21 in several cancer lines, suggesting potential role of HSP70-BAG3 complex in suppression of senescence." (PMID 32121660, 2020). "Both BAG3 and GLS are often highly expressed and play pro-survival activity in cancer cells." (PMID 30910998, 2019). "Using genetic models, we recently made an important discovery that some cancer-specific effects of Hsp70 result from its direct interaction with a co-chaperone Bag3, rather than from its core chaperone function." (PMID 29445088, 2018). "Additionally BAG3 has been reported to regulate epithelial-mesenchymal transition (EMT) and metastasis in a variety of cancer models." (PMID 29644001, 2018). "In addition, we found that BAG3 silencing sensitized EqS04b cells to phenethylisothiocyanate (PEITC), a promising cancer chemopreventive/chemotherapeutic agent present in edible cruciferous vegetables." (PMID 23876161, 2013). "Thus, it is not very surprising that the interaction of HSP70 with BAG3 is considered as a potential therapeutic target in anti-cancer therapy." (PMID 28680391, 2017). "Regardless of Mcl-1-dependency specific knock-down of Bag3 sensitizes cancer cells to the cytotoxic effects of ABT263 and ABT737, suggesting that interference with Bag3 may be useful to chemo-sensitization." (PMID 26474387, 2015). "Moreover, BAG1 and BAG3 have been involved within the Mitogen-Activated Protein Kinase (MAPK) pathway, principally through c-RAF activation, and separate studies confirmed either BAG1 or BAG3 deregulation in diverse cancer types." (PMID 22016818, 2011). "Thus, protection of BAG3 from proteolysis has a selective anti-apoptotic outcome, interacting with chaperone and non-chaperone pro-survival pathways in stressed cancer cells." (PMID 19352495, 2009). "Finally, through gene expression analysis, we identified signaling molecules that might contribute toward TRAIL and MSC-TRAIL resistance in CD133+ CSCs, and uncovered NFKB1, BAG3, MCL1, GADD45A, and HRK as potential anti-cancer genes that could increase sensitivity of NSCLC to MSC-TRAIL therapy." (PMID 31466290, 2019). "BAG3, a member of the co-chaperone family, is a well-known non-HSP substrate of HSF1 and contributes to chemoresistance in cancer." (PMID 39850800, 2024). "However, the functional roles of BAG3 and DEDD2 in cancer cell response to HSP90 inhibition are not explored." (PMID 23615731, 2013).
tumor (86 papers, 2011 to 2026). "This stabilization is inextricably linked with the establishment of an M2-polarised microenvironment by tumour-associated macrophages because BAG3 enhances the survival-signalling and cytokine networks that are conducive to alternative activation." (PMID 41562074, 2025). "In this study, BAG3 expression data integrated from numerous prior publications were reassessed, underscoring its widespread and robust association with tumor biology." (PMID 41367874, 2025). "Among upregulated genes in PDOs derived from basal-like tumors were genes that have been associated with tumor progression or cell survival including BAG3 (log-rank p = 0.0015), DUSP14 (log-rank p = 0.014), and LYPD3 (log-rank p = 0.013)." (PMID 39363341, 2024). "Bcl-2 Associated Athanogene 3 (BAG3) is overexpressed in several tumors, and it is related to the growth, invasion, metastasis, drug resistance of tumor cells, and prognosis of the patients, making BAG3 a potential therapeutic target." (PMID 36228497, 2022). "Little is known, however, of the function of this chaperone complex in highly dividing tumor cells where BAG3 has been linked to cytoskeletal dynamics." (PMID 26496431, 2015). "BAG3 staining was significantly associated with tumor size (P = 0.027) and tumor TNM stage (P = 0.004)." (PMID 24895585, 2014). "BAG3 over-expression has been linked in many studies to chemotherapy resistance, where an enhanced ability to form autophagosomes and initiate autophagic flux is protective against the anti-tumor actions of the chemotherapeutic drug." (PMID 35035775, 2022). "Furthermore, BAG3 overexpression has been associated with actin reorganization and increased cell motility of several human tumor cell lines." (PMID 35406724, 2022). "BAG3 protein expression was associated with tumor size and gender (P = 0.001, P = 0.038); a greater proportion of females had tumors with high BAG3 scores than males and also patients with tumor size more than 5 cm had high BAG3 scores." (PMID 30081850, 2018). "While BAG3 positivity correlates with tumor grade in some contexts, BAG3-negative tumors likely depend on alternative molecular alterations or signaling inputs from the microenvironment to maintain viability." (PMID 41367874, 2025). "Neutralizing BAG3 with monoclonal antibodies has been shown to reduce fibrosis, inhibit tumor growth, and enhance the efficacy of immunotherapy by improving immune cell infiltration and activation." (PMID 40507324, 2025). "Stress-related genes, HSPB1 and BAG3, were expressed at higher levels in both tumor and paracarcinoma tissues in the NMPR_Pre-NAIC group compared to the MPR_Pre-NAIC group." (PMID 40295492, 2025). "Nevertheless, the widespread secretion of BAG3 by tumors emphasizes its critical role in shaping the tumor microenvironment." (PMID 41367874, 2025). "Immunohistochemical analysis confirmed widespread high BAG3 expression across multiple tumor types, often correlating with tumor grade." (PMID 41367874, 2025). "Melanoma studies have also revealed that BAG3 positivity correlates with tumor aggressiveness and sustains NF-κB activation, further contributing to chemotherapy resistance." (PMID 40507324, 2025). "In this study, BAG3 expression was evaluated in 104 HNSCC samples from various tumor sites, and samples with high BAG3 expression were found to have a significantly higher risk of recurrence compared to BAG3-negative samples." (PMID 40507324, 2025). "The distribution of BAG3 score immunoreactivity was also evaluated across patients with tumor grades ranging from low (G1) to high (G3)." (PMID 40507324, 2025). "Our data reveal that BAG3 is both expressed and secreted by 24 tumor cell lines from diverse origins, highlighting the need for further investigation into its role in tumor growth in vitro." (PMID 41367874, 2025). "Following immunohistochemical staining, 104 paraffin-embedded primary tumor samples from therapy-naive patients were evaluated for BAG3 protein expression." (PMID 40507324, 2025).
tumor (continued). "Subsequently, we analyzed the relationship between USP32 and BAG3 using the percentage of positive tumor cells of USP32 and BAG3, and found that the expressions of USP32 and BAG3 in NSCLC tissues were significantly positively correlated." (PMID 39030175, 2024). "In order to transfer these findings into a more complex model, the influence of BAG3/YAP1‐signaling on tumor growth was validated in an OTC transplantation model." (PMID 38655699, 2024). "The effects of HSPB8 and BAG3 on lung metastasis of tumors in vivo were verified by constructing a metastatic tumor model." (PMID 39215616, 2024). "The observation of fibroblast-activated protein (FAP) positive cells in infiltrated bone marrow specimens co-expressing BAG3 further support the involvement of the protein in fibroblast-mediated tumor survival." (PMID 39198407, 2024). "We also use the TIMER database to investigate the link between BAG3 expression and tumor-infiltrating immune cell gene markers in KIRC." (PMID 38297320, 2024). "Based on these results, patients with KIRC presenting lower BAG3 expression seemed to have a more advanced tumor stage." (PMID 38297320, 2024). "This interesting observation provokes the question inasmuch BAG3's oncogenic functions are mediated by antagonizing the tumor suppressor function of cilia." (PMID 38655699, 2024). "BAG3 expression was substantially correlated with the majority of immune markers in various types of immune cells in KIRC after correcting for tumor purity." (PMID 38297320, 2024). "We found that compared with normal tissues, the expression level of BAG3 mRNA was considerably decreased in tumor tissues." (PMID 38297320, 2024). "When cultured in spheroid cell medium as tumor spheres, U251 cells exhibit increased levels of endogenous BAG3." (PMID 38655699, 2024). "Because BAG3 increases the proliferation and survival of tumor cells, it is possible that BAG3 plays a significant role in the progression of tumors." (PMID 39030175, 2024). "Next, we compared BAG3 protein–protein interactions in cells grown as tumor spheres and cells grown in adherent culture." (PMID 38655699, 2024). "Exposure to the proteasome inhibitor, bortezomib, has some effect on the tumor but also increases the levels of tissue BAG3 and its related chaperones." (PMID 36980278, 2023). "Treatment with inhibitory BAG3 antibody resulted in tumor regression and metastatic inhibition in three independent mouse models." (PMID 37444617, 2023). "Among alarmins, one came to our attention for the pro-tumour role shown in pancreatic adenocarcinoma (PDAC): BAG3 protein." (PMID 37554328, 2023). "Further, treatment with a murine anti-bag3 antibody resulted in lower numbers of stromal macrophages suggesting that the antibody can prevent macrophage activation and infiltration of the tumor stroma, as well as reduced growth and metastasis." (PMID 36980278, 2023). "Increased BAG3 allows for increased coupling with Hsp70 which supports tumor growth, whereas impaired coupling of BAG3-Hsp70 opposes tumor growth." (PMID 36980278, 2023). "BAG3 is constitutively expressed in several primary tumors and tumor cell lines, including PDAC, where it plays a prosurvival role through various mechanisms according to the cellular context." (PMID 37444617, 2023). "Further evidence for the role of BAG3 in tumor progression comes from studies using inhibitors of the BAG3-Hsp70 interaction." (PMID 36980278, 2023). "The combined effect shown here on tumor growth and metastasization following the BAG3 and SIRPα blockade provides further evidence of the versatility of the anti-BAG3 tools in combination therapies." (PMID 35241649, 2022). "High bag3 expression is significantly and positively correlated to the fibrotic characteristic of the tumor types analyzed." (PMID 34741483, 2022). "Our findings are consistent with that of other studies, which showed increased BAG3 expression in cardiomyocyte and tumor cell lines exposed to hypoxia." (PMID 36142618, 2022).
tumor (continued). "Reportedly, BAG3 is highly expressed in the tumor tissues of patients with BC, and its high expression indicates a poor prognosis of the patients; knocking down BAG3 significantly suppresses the growth and migration of BC cells." (PMID 36228497, 2022). "A monoclonal antibody able to bind extracellular BAG3 can block its activity and to impair the tumor growth and the metastatic process in three different PDAC mouse models, thus confirming the relevance of the protein in the neoplastic cells—TAMs cross talk." (PMID 34741483, 2022). "This increases the relevance of Bag3 compared to other Bag proteins, as inhibition of apoptosis by autophagy is central to tumor resilience." (PMID 36077131, 2022). "All this evidence highlights the crucial value of BAG3 modulation in the field of tumor pathologies and its potential impact on the development of future anticancer strategies." (PMID 35163936, 2022). "Basal expression of BAG3 is elevated in several tumor cell lines, where it promotes cell survival signaling and apoptosis resistance through the interaction with many protein partners." (PMID 35163936, 2022). "An aspect, possibly affecting tumor biology, less considered so far, is the effect of the bag3 gene copy number variation (CNV) in different tumors." (PMID 34741483, 2022). "Our starting point was the observation that JG-98 that suppressed tumor infiltration of macrophages can block the interaction of Hsp70 with Bag3, suggesting that Bag3 can be involved in this effect." (PMID 36077705, 2022). "The anti-BAG3 + anti-SIRPα mAbs treatment inhibited (p = 0.007) tumor growth by about the 70%; also the number of metastatic lesions was decreased, mostly by the effect of the anti-BAG3 mAb." (PMID 35241649, 2022). "More recently, new pieces of evidence revealed a pivotal role of extracellular BAG3 in pro‐tumor cell signaling in the tumor microenvironment, as well as its involvement in the development of fibrosis in tumor tissues." (PMID 34741483, 2022). "In the ex vivo analysis, we found that the treatment with either anti-BAG3 or anti-SIRPα mAb resulted in a reduction of tumor weight, which was more impressive when the two antibodies were used in combination." (PMID 35241649, 2022). "The disruption of the crosstalk between tumor cells and TAMs due to CSF1 and BAG3 depletion in an orthotopic PDAC tumor model enhanced Tc infiltration and activation, proving the importance of those soluble factors." (PMID 32823814, 2020). "The discovery of a secreted BAG3 opened a new field of investigation on tumor development and progression, revealing a role for BAG3 in a new signaling pathway mediated by the BAG3/BAG3 receptor axis, which also includes monocytes and other stromal cells." (PMID 33114371, 2020). "The current study demonstrates that BAG3 produced by stromal cells plays a different role, focusing on tumour microenvironment." (PMID 31119886, 2019). "The current study demonstrated that beside PDAC tumour cells, BAG3 was also expressed in some activated stroma cells in PDAC tissue, as well as in activated PSCs." (PMID 31119886, 2019). "The block of this paracrine loop through an anti‐BAG3 antibody reduces tumor cell proliferation, tumor growth, and metastasis formation." (PMID 30973679, 2019). "BAG3 protein induces endothelial vascular remodeling and tumor formation via the phosphorylation of ERK (extracellular signal-related kinase) in the Raf/MEK/ERK pathway." (PMID 30081850, 2018). "Their expression levels in BAG3-silenced cells were confirmed by qRT-PCR and western blot analyses, disclosing two novel targets of BAG3 pro-tumor activity." (PMID 29487711, 2018). "BAG3 protein is also highly expressed in different tumor types and regulates neoangiogenesis by interacting with and regulating ERK activity." (PMID 29955247, 2018).
tumor (continued). "Histopathological review of the sections revealed increased tumour epithelial BAG3 expression was demonstrable in 37/80 cases compared to the surrounding stromal tissue and these were graded as high BAG3 expressing tissues (Score 2, 3)." (PMID 29644001, 2018). "BAG3 protein is an anti-apoptotic factor that sustains cell survival in several tumor types and is involved in different cellular processes including autophagy, cell stress response, proliferation, migration and Epithelial-Mesenchymal Transition (EMT)." (PMID 29487711, 2018). "In this study we describe a novel role for BAG3 in driving tumour proliferation in TNBC by stabilising EGFR signalling transduction pathways." (PMID 29644001, 2018). "We observed a reduction in AKT activation and a decrease in activation of downstream AKT target, pIKKα/β which has been previously reported to be stabilised by BAG3 and regulate tumour cell proliferation." (PMID 29644001, 2018). "JNK signaling led also to the activation of the c-Jun transcription factor, which is involved in the upregulation of several genes, among them, the BAG3 protein that exerts an important role in endothelial cell survival and growth and in tumor neoangiogenesis." (PMID 29955247, 2018). "In this study, we identified a pro-survival signalling protein BCL2- associated athanogene 3 (BAG3) to be highly expressed in a subset of TNBC cell lines and tumour tissues." (PMID 29644001, 2018). "In our series, we identified a subgroup composed by 26 patients for whom we had information about BAG3 staining in primary tumours and metastasis." (PMID 29113311, 2017). "Our analysis revealed that BAG3 expression is significantly enhanced in metastatic lesions as compared to primary tumours in this subgroup of patients." (PMID 29113311, 2017). "To BAG3 protein was assigned a role in sustaining the growth and in contributing to chemotherapy resistance in some tumour types." (PMID 29113311, 2017). "BAG3 is an evolutionarily conserved co-chaperone expressed at high levels and has a prosurvival role in many tumor types." (PMID 28703799, 2017). "Collectively, the current study established a tumor suppressor-like function of BAG3 via direct interaction with G6PD in HCCs at the cellular level." (PMID 26621836, 2016). "Blockade of this cascade using an anti‐BAG3 antibody diminished primary tumor growth and metastasis." (PMID 26747091, 2016). "The current study demonstrated that BAG3 elevation exhibited a tumor suppressor-like effect on proliferation of HCCs at the cellular level." (PMID 26621836, 2016). "Finallythe impact of depleting secreted BAG3 in PDAC tumours is also reflected in ageneral decrease of macrophage-released cytokines." (PMID 26522614, 2015). "This is of particular interest given that expression of BAG3 is upregulated in several primary tumors and tumor cell lines of various origins, where it is believed to support the tumor phenotype." (PMID 26496431, 2015). "Interruption of this loop through an anti-BAG3 monoclonal antibodyimpairs tumour growth and metastasis formation." (PMID 26522614, 2015). "Both motifs have been shown to contribute to the signaling effects of BAG3 on cell adhesion, actin assembly and motility of tumor cells." (PMID 26496431, 2015). "Here, the authors showthat BAG3 secreted from tumour cells binds to and activates macrophages, which in turnpromotes cell growth, and an antibody blocking BAG3 binding reduces tumour formation inmice." (PMID 26522614, 2015). "While studying expression of BAG3 in PDACs we noticed that pancreatic islets in normal pancreatic tissue surrounding the tumor strongly stained for BAG3, we therefore decided to further investigate the role of this protein in endocrine pancreatic cells." (PMID 25766323, 2015). "Our in vivo experiments stronglysupport the tumour promoting effect of circulating BAG3 via modulating macrophageresponses." (PMID 26522614, 2015).